TANAR (TWIST1 associated long noncoding RNA regulated by androgen receptor)
Gene: Long non-coding RNA gene on chromosome 2 (240,981,515 to 240,986,072, reverse strand). Ensembl gene ENSG00000223991.
Diseases named in the same sentence as TANAR in open-access papers:
TANAR is named in the same sentence as 2 diseases in open-access papers, as found by Europe PMC text mining. Sharing a sentence is not in itself a finding about the gene and the disease.
TANAR shares sentences with these, for which no sentence is quoted: tumor (2 papers); kidney cancer (1).